MIR377 (microRNA 377)
Synonyms: hsa-mir-377; MIRN377; mir-377
Gene: MicroRNA gene on chromosome 14 (101,062,050 to 101,062,118, forward strand). Ensembl gene ENSG00000199015.
Gene Ontology:
Biological process: miRNA-mediated post-transcriptional gene silencing
Cellular component: RISC complex
Homologues: Orthologues: chimpanzee ptr-mir-377 (100% identical), guinea pig MIR377 (97% identical), mouse Mir377 (97% identical), rabbit MIR377 (96% identical). Paralogues in human: MIR539 (80% identical), MIR494 (74% identical), MIR382 (72% identical), MIR381 (71% identical), MIR154 (68% identical), MIR487A (68% identical), MIR410 (67% identical), MIR1185-1 (65% identical), MIR496 (65% identical), MIR1185-2 (64% identical), MIR323B (64% identical), MIR323A (62% identical), and 4 more.